RRAGC-DT (RRAGC divergent transcript)
Synonyms: LENGA
Gene: Long non-coding RNA gene on chromosome 1 (38,859,886 to 38,965,038, forward strand). Ensembl gene ENSG00000228436.
Diseases named in the same sentence as RRAGC-DT in open-access papers:
RRAGC-DT is named in the same sentence as 5 diseases in open-access papers, as found by Europe PMC text mining. Sharing a sentence is not in itself a finding about the gene and the disease.
RRAGC-DT shares sentences with these, for which no sentence is quoted: atrial fibrillation (1 paper); cancer (1); gastric cancer (1); Myocardial fibrosis (1); tumor (1).